VCAM1 (vascular cell adhesion molecule 1)
Diseases named in the same sentence as VCAM1 in open-access papers (continued):
Sharing a sentence is not in itself a finding about the gene and the disease.
renal disease (31 papers, 2012 to 2026). "Urinary VCAM-1 holds promise as a non-invasive predictor of underlying active renal disease; a strong association between urinary VCAM-1 and NIH renal histology AI was displayed in two separate studies (r = 0.42 and r = 0.97; p = 0.05 and p < 0.001, respectively)." (PMID 36233628, 2022). "Vcam1 facilitates leukocyte recruitment in renal diseases, Apoe influences lipid metabolism and renal function risk, and Cystatin C acts as a biomarker for renal function, indicating impaired kidney function when elevated." (PMID 41567268, 2026). "Taken together, these findings validate our approach to enrich for important regulatory regions and highlight the potential relevance of the PT_VCAM1 state in renal disease and declining kidney function." (PMID 38347009, 2024). "Two genes (C3 and VCAM1) were of particular interest given previous descriptions of their potential use as biomarkers in kidney disease." (PMID 37580326, 2023). "Another puzzle piece in stage 2 is the exclusive detection of vascular cell adhesion protein 1 (VCAM-1), a biomarker of kidney diseases." (PMID 35884827, 2022). "VCAM-1 was also elevated in the urine of mice with experimentally induced immune nephritis, showing a good correlation with disease activity and the strains that developed more severe kidney disease also had higher urinary VCAM-1 levels." (PMID 33292825, 2020). "Again, urine angiostatin showed a higher specificity, sensitivity, positive and negative predictive values in differentiating active renal from active non-renal disease than CXCL4 or VCAM-1." (PMID 29325582, 2018). "This is consistent with the current study in Chinese patients showing that urinary VCAM-1 levels were elevated in active LN, and differentiated active renal from non-renal disease." (PMID 29325582, 2018). "In this study, we showed that the novel urinary biomarkers angiostatin, CXCL4 and VCAM-1 differentiate active renal from active non-renal disease in patients with SLE." (PMID 29325582, 2018). "Of both, higher levels of VCAM-1 in urine could be indicative of a long-term renal function loss, while ALCAM could be used as a potential biomarker of kidney disease." (PMID 34281193, 2021). "The overexpression of VCAM-1 in tubules of renal diseases has been reported." (PMID 33407253, 2021). "VCAM-1 is expressed by tubular cells in inflamed kidneys in multiple renal diseases, including LN." (PMID 31594956, 2019). "Blockade of these pathways may reduce monocyte adhesion via VCAM-1 suppression and attenuation of the inflammatory responses in renal diseases." (PMID 23153039, 2012). "Urinary vascular cell adhesion molecule-1 (VCAM1), platelet factor-4 (PF4), and the best-performing activated leukocyte CAM (ALCAM) were recently demonstrated as potential biomarkers of kidney disease activity in a cSLE cohort." (PMID 37893559, 2023). "In a cohort of 227 SLE patients (80 inactive SLE, 67 active non-renal, and 80 active renal disease) and 53 controls, VCAM-1 was significantly higher in urine from patients with active renal disease compared to patients with active non-renal disease." (PMID 34281193, 2021). "Urinary angiostatin, CXCL4 and VCAM-1 (normalized for creatinine) were significantly higher in patients with active renal disease than in patients with active non-renal disease, patients with inactive SLE and controls." (PMID 29325582, 2018). "Importantly, urinary VCAM-1 and MCP-1 levels were significantly elevated in the active renal disease group as compared with healthy controls and patients with inactive renal disease." (PMID 22788914, 2012). "Importantly, patients with active renal disease exhibited statistically significantly higher mean levels of creatinine-normalized MCP-1 and VCAM-1, compared with the other SLE patients; in contrast, urine CXCL16 was not as discriminatory." (PMID 22788914, 2012).
renal disease (continued). "Although the numbers of each type of renal disease control are rather limited, and are not completely matched with the LN patients with respect to renal function, age or gender, these preliminary findings warrant a more thorough investigation of urinary VCAM-1 levels in other renal diatheses." (PMID 22788914, 2012). "Recent single-nucleus transcriptomic profiling of mouse IRI-kidneys identified vascular cell adhesion molecule 1 (VCAM1) as a marker of non-repairing proximal tubular cell state, and Vcam1 induction has been observed in multiple forms of human kidney diseases, including allograft rejection." (PMID 34279220, 2021).
retinopathy (12 papers, 2020 to 2025). "We also measured several emerging markers of retinopathy risk such as VCAM-1, ox-LDL, hsCRP in a sub-group of patients and other hormones associated with Klotho such as FGF-23 and vitamin D which were not significantly different between groups." (PMID 33225726, 2020). "Therefore, we next looked for the direct role of VCAM-1 on pathological retinal neovascularization in a murine model of oxygen-induced retinopathy." (PMID 37179352, 2023). "In addition, the association of these SNPs with the levels of AGEP, VCAM-1, HIF-1α, VEGF, and CTRP3 in serum was investigated to understand their effects on the progression of retinopathy among diabetic patients." (PMID 35969320, 2022). "Therefore, understanding the direct involvement of VCAM-1 controlled signaling in pathological retinal neovascularization may thus offer up advanced therapeutic approaches for proliferative retinopathies." (PMID 37179352, 2023). "In our studies, we observed an induced expression of VCAM-1 in the hypoxic retina of mice exposed to OIR, suggesting the importance of VCAM-1 in proliferative retinopathies." (PMID 37179352, 2023). "These pathways could lead to osmotic vascular damage and retinopathy by activation of mitogen activated protein kinases (MAPKs), inducing the production of ICAM-1 and VCAM-1, and the breakdown of the vascular junction proteins." (PMID 38790059, 2024). "In addition, VCAM-1 via JunB-CXCL1 signaling regulates vessel anastomosis and tufts formation in mouse model of oxygen-induced retinopathy." (PMID 37179352, 2023). "Diabetic patients without retinopathy had significant elevations in the serum levels of AGEP (1077.60%, p < 0.0001) and VCAM-1 (223.29%, p < 0.0001) in association with a significant reduction in the serum level of CTRP3 (40.09%, p < 0.0001), compared to the control subjects." (PMID 35969320, 2022).
kidney (11 papers, 2011 to 2026). "Vcam1 upregulation promotes kidney inflammation by mobilizing immune cells that express its receptor CD49d." (PMID 40516868, 2025). "The LMP7-dependent up-regulation of CXCL1, CXCL2, CXCL3 and VCAM-1 expression leads to alternations in the microenvironment of tumors and progression of colorectal carcinogenesis." (PMID 28881574, 2017). "Meanwhile, the expressions of GGT-1, ICAM-1 and VCAM-1 were significantly decreased in the whole aorta plaques." (PMID 25326709, 2014). "Furthermore, ROCK2 enhances the expression of adhesion molecules such as intercellular adhesion molecule-1 (ICAM-1) and vascular cell adhesion molecule-1 (VCAM-1) in endothelial cells, fostering a proinflammatory microenvironment that promotes leukocyte infiltration and perpetuates kidney injury." (PMID 41311514, 2026). "Collectively, our results provided novel insight into the downstream mechanism of the IL-6 signaling pathway in PM-induced aorta inflammation, that is, ICAM-1 and VCAM-1-dependent monocyte adhesion." (PMID 34336088, 2021). "Berberine increased IKBα and decreased NF-κBp65 protein levels in diabetic mouse kidney, as well as inhibiting renal AGE generation and downregulating TGF-β1, ICAM-1, and VCAM-1 protein expression." (PMID 23935673, 2013).
neurodegenerative disease (10 papers, 2020 to 2025). A disorder of the central nervous system characterized by gradual and progressive loss of neural tissue and neurologic function. "In the CNS, VCAM-1 is one extensively studied adhesion molecule, which is involved in Th1 cell capture and arrest by the CNS endothelium, and implicated in T cell-mediated neuroinflammatory and neurodegenerative diseases." (PMID 38317227, 2024). "In contrast, in experimental neurodegenerative disease and age-related cognitive dysfunction models, treatment with dietary supplements of alpha lipoic acid resulted in downregulation of VCAM1, reduced inflammatory cell infiltration into the CNS and improved memory." (PMID 38827116, 2024). "Similarly, microvascular injury biomarkers such as vascular cell adhesion molecule-1 (VCAM-1) and intracellular adhesion molecule-1 (ICAM-1) are released during global and regional cerebral hypoperfusion, a phenomenon associated with neurodegenerative diseases like AD." (PMID 32943089, 2020).
neurological diseases (10 papers, 2014 to 2025). "Cell adhesion molecules, including ICAM-1 and VCAM-1, play an important role in neurological diseases." (PMID 35208996, 2022). "By manipulating Vcam1 levels, we could potentially improve the retention of quiescent NSCs and enhance regenerative capacities in conditions of aging and neurological disorders." (PMID 40683857, 2025). "MMPs are known to contribute to the neuro-inflammatory response in many neurological diseases, and induction of MMP-2 is mediated by the binding of vascular cell adhesion molecule-1 on VECs to the very late activation-4 antigen expressed on T cells and macrophages." (PMID 30463256, 2018).
bacterial infection (8 papers, 2012 to 2023). "In addition to the increase of inflammatory cytokines, the activation of endothelial cells by LPS was also indicated by the abundant expression of molecules such as ICAM‐1 and VCAM‐1 which are known to mediate the immune response in endothelial cells in response to bacterial infections." (PMID 29210175, 2018). "On the other hand, VCAM1, PLA2G2A and PLA2G10, down-regulated genes, maintain, amongst other functions, close relationships with the defensive host response in the face of bacterial infection, inflammation and immune response regulation/suppression situations." (PMID 32764374, 2020). "Bacterial infections are frequently detected around the portal tracts of PSC patients and elevated serum endotoxin can increase the expression of adhesion molecules such as VCAM-1 and ICAM-1." (PMID 37820623, 2023). "Our single-cell transcriptomics enable delineation of MΦ phenotypes in granulomas and infected tissues during persistent intracellular bacterial infection that have not been defined, such as the bone marrow–derived VCAM-1+ granuloma MΦ population and ACE+ granuloma MΦ population." (PMID 36608122, 2023).
metabolic disorders (8 papers, 2014 to 2025). "We demonstrate that the efficient capture of VCAM-1+ endothelial cell populations and their associated extracellular vesicles has the potential to shed light on the early molecular events that precede cardiovascular and metabolic diseases." (PMID 39698414, 2024). "This novel technology opens up exciting possibilities for further research into the role of cell adhesion molecules like VCAM-1 in vascular pathology and metabolic disease." (PMID 39698414, 2024). "Circulating inflammatory biomarkers such as CRP, IL-6, TNF-α, monocyte chemotactic protein 1 (MCP-1), intercellular adhesion molecule 1 (ICAM-1), vascular cell adhesion protein 1 (VCAM-1), and E-selectin have been associated with a variety of metabolic disorders and associated outcomes." (PMID 24911359, 2014). "Isolation of VCAM-1+ EC-EV from heterogeneous sources such as conditioned cell culture media holds promise for subsequent detailed characterization, and may facilitate the study of VCAM-1+ EC-EVs in cardiovascular and metabolic diseases, for disease monitoring and therapeutic insights." (PMID 39698414, 2024).
vascular disorder (8 papers, 2014 to 2025). A general term used to describe any disease affecting blood vessels]. "Soluble adhesion molecule markers, such as ICAM-1, ICAM-3, and VCAM1, and inflammatory cytokine and markers like neopterin have been used as possible biomarkers of vasculopathy in JDM." (PMID 37957619, 2023). "Moreover, the vascular disorders induced more adhesion molecules, such as vascular cell adhesion molecule 1 (VCAM-1) and intracellular adhesion molecule 1 (ICAM-1), were thought to play an important role in controlling the pathological process of ECs inflammation." (PMID 26063980, 2015). "First, baseline serum levels of VCAM-1, E-selectin, ACE2 and Lp-PLA2 were retrospectively measured to evaluate the degree of vascular disorders with endothelial cell activation and to compare them among study sub-cohorts." (PMID 38276214, 2024). "In the present study, pro- inflammatory molecules as ICAM-1 and VCAM-1 were markedly elevated in diabetic patients with PVD and had a negative correlation with A/BI in vasculopathy." (PMID 25287126, 2014).
heart disease (7 papers, 2015 to 2024). "In many human heart diseases, factors such as reactive oxygen species and hemodynamics can enhance the expression of VCAM-1 in the heart, and cell infiltration and inflammation in the heart tissue can lead to continuous heart remodeling, fibrosis, and dysfunction." (PMID 36675472, 2023). "Others have suggested that VCAM-1 was a poor predictor of heart disease outcomes." (PMID 28667255, 2017). "Therefore, up-regulation of VCAM-1 expression on cytokine-triggered heart diseases may be the key factor responsible for the targeted leukocyte transmigration into extra-vascular space of inflammation." (PMID 26858641, 2015). "Therefore, cytokine-triggered VCAM-1 up-regulation in heart diseases may be the key response for the targeted leukocyte transmigration into extravascular space of inflammation." (PMID 26173590, 2015). "The results provide new insights to understand the mechanisms by which TNF-α stimulated VCAM-1 expression in HCFs associated with amplifying the inflammatory responses, supporting the hypothesis that TNF-α may play a key role in the exaggeration of cardiac diseases." (PMID 26858641, 2015). "The results provide new insights into the mechanisms of TNF-α action on HCFs to up-regulate the VCAM-1 expression and then amplified the inflammatory responses, supporting the hypothesis that TNF-α may play a key role in the development of cardiac diseases." (PMID 26173590, 2015).
brain disorder (5 papers, 2017 to 2024). A disease affecting the brain or part of the brain. "rs12185519 was mapped to KDM4B, which has the potential to inhibit brain diseases such as AD by blocking ICAM1 and VCAM1‐induced extravasation." (PMID 39300745, 2024). "Our data suggest the potential of KDM4B inhibition for brain disease such as AD by blocking ICAM1 and VCAM1-induced extravasation." (PMID 28327608, 2017). "Similarly, vascular cell adhesion molecule-1 (VCAM-1) has been effectively targeted and imaged using antibody-functionalized iron oxides in a variety of brain disorders." (PMID 28509283, 2017).
infectious disease (4 papers, 2008 to 2020). A disorder directly resulting from the presence and activity of a microbial, viral, or parasitic agent in humans. "Soluble forms of cell surface molecules such as sE-selectin, intercellular adhesion molecule-1 (ICAM-1) and vascular cell adhesion molecule-1 (VCAM-1) are released from ECs after activation and are used as diagnostic and prognostic markers in infectious diseases." (PMID 26462910, 2015). "In fact, in infectious diseases dysregulation of numerous ADAM substrates such as junction molecules (e.g., E-cadherin, VE-cadherin, JAM-A), adhesion molecules (e.g., ICAM-1, VCAM-1, L-selectin), and chemokines and cytokines (e.g., CXCL16, TNF-α) has been observed." (PMID 33392273, 2020).
adenocarcinoma (3 papers, 2007 to 2022). A common cancer characterized by the presence of malignant glandular cells. "Additionally, in comparison with normal samples, the expression level of CCR7, CXCL10, IDO1, and MMP9 were increased in phases of adenocarcinoma’s tissue, while the expression level of CXCL9 and VCAM1 were decreased." (PMID 31214045, 2019).
benign tumors (3 papers, 2014 to 2016). "A combination of HE4, CA125, carcinoembryonic antigen (CEA), and vascular cell adhesion molecule (VCAM)-1 in an assay panel has been tested for detecting early stage OVC versus benign tumors, and achieved 86 % sensitivity." (PMID 27036110, 2016). "The deleterious effects of TNF-α on fibroblasts may aggravate heart inflammation mediated through the up-regulation of adhesion molecules such as vascular cell adhesion molecule-1 (VCAM-1)." (PMID 26173590, 2015). "An assay that detects a combination of HE4, CA-125, carcino-embryonic antigen-related cell adhesion molecule 5 (CEACAM5) and vascular cell adhesion molecule 1 (VCAM1) expression in serum has demonstrated significantly better sensitivity for early stage OVC detection compared to benign tumors." (PMID 25477184, 2014).
respiratory diseases (2 papers, 2013 to 2025). "Increasing evidence has revealed the involvement of inflammatory proteins, including cPLA2, COX-2, VCAM-1, ICAM-1, and MMP-9, in the production and development of respiratory diseases." (PMID 40136649, 2025).
intestinal disease (1 paper, 2025). "Antibodies directly targeting VCAM-1 present an attractive strategy for the selective blockade of VCAM-1-mediated cell recruitment during intestinal disease." (PMID 40095109, 2025).
VCAM1 also shares sentences with these, for which no sentence is quoted: multiple myeloma (11 papers); acute myocardial infarction (10); infarction (5); Parkinson disease (5); acute lung injury (4); acute myocarditis (3); ankylosing spondylitis (3); autism spectrum disorder (3); Autoimmunity (3); calcific aortic valve disease (3); cerebral infarction (3); cerebral small vessel disease (3); complication (3); intestinal tumor (3); liver (3); renal failure (3); unstable angina (3); Airway obstruction (2); Anxiety (2); aortic atherosclerosis (2); central obesity (2); chondrosarcoma (2); chronic lung disease (2); chronic periodontitis (2); chronic prostatitis (2); diabetic cardiomyopathy (2); diabetic encephalopathy (2); focal segmental glomerulosclerosis (2); gangrene (2); head and neck cancer (2).
A further 173 diseases each share a sentence with VCAM1 in 2 papers or fewer.